SOX10 (SRY-box transcription factor 10)
Diseases named in the same sentence as SOX10 in open-access papers (continued):
Sharing a sentence is not in itself a finding about the gene and the disease.
Waardenburg syndrome (49 papers, 2011 to 2026). A disorder characterized by varying degrees of deafness and minor defects in structures arising from neural crest, including pigmentation anomalies of eyes, hair, and skin. "SOX10 pathogenic variants are associated with more severe neural defects, such as olfactory bulb agenesis, frequent in Kallman and Waardenburg syndrome cases." (PMID 41516007, 2025). "The SOX10 gene is associated with Waardenburg syndrome, and we identified two novel SOX10 variants (c.393C>G, p.N131K, and c.535A>T; p.K179X) in two cases." (PMID 39336818, 2024). "Neurocristopathies can be caused by pathogenic variants of master neural crest regulators, for example, SOX10 in Hirschsprung’s disease and Waardenburg syndrome or PAX3 in Waardenburg syndrome." (PMID 39418292, 2024). "The HMG box position 58 had ClinVar variants in the SOX10 homologous SOXE member linked to pathogenic annotation for Waardenburg syndrome type 2E, and SOX17 was also associated with disease due to changes at this site." (PMID 36672963, 2023). "Pathogenic variants in SOX10 are associated with Waardenburg Syndrome, a rare group of disorders associated with sensorineural hearing loss and pigmentation deficiencies." (PMID 36517585, 2023). "The association of the SOX10 gene with congenital disorders was initially recognized in the context of Waardenburg–Shah syndrome, a subtype of Waardenburg syndrome (WS), also known as Waardenburg–Hirschsprung syndrome and WS type 4." (PMID 38132479, 2023). "The only complex-type patient with a SPAST variant also had a SOX10 variant, which is the causative gene in Waardenburg syndrome." (PMID 37251230, 2023). "Waardenburg syndrome is genetically heterogeneous and results from mutations in Sox10, Pax3, Mitf, Snai2, Ednrb, and Edn3, as well as many cases with unidentified mutations." (PMID 32912160, 2020). "Mutations in SOX10 cause Waardenburg syndrome, which is characterized by developmental anomalies of the eye." (PMID 31172260, 2019). "This is the first truncating mutation in exon 3 of SOX10 that is associated with neurological symptoms in Waardenburg syndrome." (PMID 29792164, 2018). "For example, EDNRB and SOX10 mutations together cause human Waardenburg syndrome." (PMID 40002960, 2025). "A homozygous SOX10 deletion was found to cause a severe form of four-limb arthrogryposis but, rather than representing hypomorphic variants, it was a co-dominant occurrence and parents were both affected by Waardenburg syndrome." (PMID 38397148, 2024). "It is interesting that hearing loss due to hypoplasia/dysplasia of the semicircular canals is very rare, but is a typical sign of another SOXopathy (Waardenburg syndrome caused by SOX10 mutations) and may hint at a connection between these two conditions." (PMID 38397148, 2024). "Signs of Kallmann syndrome (KS) have also been observed in Waardenburg syndrome, suggesting that KS may result from SOX10 mutations." (PMID 38132479, 2023). "The Sox transcription factor Sox10 is also crucial for melanocyte development, where it contributes to melanocyte fate-specification by transcriptional activation of Mitf, consistent with the association of SOX10 with Waardenburg syndrome in humans." (PMID 21909283, 2011). "Genetic studies suggest that Waardenburg syndrome is caused by mutations of PAX3 and other genes such as MITF, SOX10, EDN3, EDNRB and SNAI21,9,13,35–37." (PMID 38278860, 2024). "PWCH (Peripheral demyelinating neuropathy, central demyelinating leukodystrophy, Waardenburg syndrome, and Hirschsprung disease) represents a neurological variant of the previously discussed WS4, where a SOX10 mutation is also implicated." (PMID 38132479, 2023). "Mutations in the gene encoding the transcription factor SOX10 are associated with WS4, which is a subtype of a family of Waardenburg syndromes." (PMID 36003149, 2022). "Four had Waardenburg syndrome (WS)-II type A and type E, caused by MITF and SOX10 gene variants, respectively." (PMID 36568381, 2022).
Waardenburg syndrome (continued). "Haploinsufficiency in one of the AP-2 targets, the SoxE family member SOX10, results in Waardenburg syndrome; patients exhibit defects in the peripheral and enteric nervous systems and also pigmentation defects." (PMID 31199790, 2019). "Humans are particularly susceptible to haploinsufficient mutations in a number of neural crest-specific genes, including sox10, leading to Waardenburg syndrome or Hirschsprung disease, whereas this is less the case in zebrafish." (PMID 31199790, 2019). "Furthermore, heterozygous SOX10 (OMIM #602229) mutations can lead to peripheral demyelinating neuropathy, central dysmyelination, Waardenburg syndrome and Hirschsprung disease (OMIM #609136)." (PMID 39769160, 2024). "Genetic variants within SOX2 are associated with anophthalmia and neural alterations, SOX3 with altered pituitary development, SOX10 with Waardenburg syndrome and Hirschsprung’s disease, SOX11 with Coffin–Siris syndrome, and SOX18 with Hypotrichosis–Lymphedema–Telangiectasia Syndrome (HLTRS)." (PMID 36672963, 2023). "However, in the phenotypically similar Waardenburg syndrome in humans, these phenotypes are associated with EDN3, SOX10, and EDNRB." (PMID 32616020, 2020). "Six genes involved in Waardenburg syndrome include PAX3 (encoding the paired box 3 transcription factor), MITF (microphthalmia-associated transcription factor), EDN3 (endothelin 3), EDNRB (endothelin receptor type B), SOX10 (encoding the Sry bOX10 transcription factor), and SNAI2 (snail homolog 2)." (PMID 35790984, 2022). "Of note, SOX10 is not a classical HLDs gene, and heterozygous variants in SOX10 lead to a very wide spectrum of phenotypes including peripheral demyelinating neuropathy, central dysmyelination, Waardenburg syndrome, Hirschsprung disease, Kallmann syndrome, and deafness." (PMID 33597727, 2021). "Moreover, in addition to coding mutations within SOX10 and other genes involved in Waardenburg syndrome, this human NCP might also be caused by alterations in enhancers surrounding SOX10." (PMID 32765580, 2020). "SOX10 variants are known to cause WS types II and IV (Hirschsprung disease as an additional finding) (MIM 613266), PCWH (peripheral demyelinating neuropathy, central demyelinating leukodystrophy, Waardenburg syndrome, and Hirschsprung disease) (MIM 609136), and Kallmann syndrome with deafness." (PMID 27562378, 2016). "Due to the presence of hypogonadism and anosmia in subtypes of Waardenburg syndrome (e.g., WS2E), SOX10 was investigated as a potential candidate gene for Kallman syndrome (KS), which falls under the umbrella of congenital hypogonadotropic hypogonadism (HH)." (PMID 38132479, 2023). "Both sox10 and mitf are involved in Waardenburg’s syndrome, which is characterized by the lack of pigmentation of the hair, eyes, and skin, and is normally associated with the deletion of sox10." (PMID 30372461, 2018). "Mutations of different genes like MITF (microphthalmia-associated transcription factor), PAX3 (Paired Box Gene 3), SOX10, and EDNRB (endothelin receptor type B, gene) have been noted in causing mild or incomplete phenotypic expression of symptoms in Waardenburg syndrome." (PMID 31998473, 2020). "Thus, possible candidates for white coat colour (KIT on BTA6, KITLG on BTA5, PMEL on BTA5, TYR on BTA29) and other Waardenburg syndromes (WS) including PAX3 (WS1, WS3; on BTA2), EDNRB (WS4a; on BTA12), EDN3 (WS4b; on BTA13) and SOX10 (WS2e, WS4c; on BTA5) could be clearly excluded." (PMID 22174915, 2011). "Although the Waardenburg syndrome genes PAX3, SOX10, MITF, EDN3 and EDNRB were not dramatically affected at the mRNA level, expression of the piebaldism gene KIT was significantly down-regulated upon loss of YY1." (PMID 22570637, 2012).
breast carcinoma (41 papers, 2006 to 2025). "The correlation with poor prognosis is linked to SOX10’s involvement in tumor development and metastatic-seeding ability in breast cancer cells." (PMID 38132479, 2023). "Breast carcinomas exhibit the greatest levels of SOX10 expression, which has been linked to stem-like properties and the promotion of mesenchymal transition." (PMID 36120242, 2022). "Biochemical and genetic analyses of the SOX10 regulatory region in SLK-deficient mammary tumor cells show that Sox10 expression is dependent on a novel −7kb enhancer that harbors three SoxE binding sites." (PMID 33985544, 2021). "SOX10 was validated as a sensitive diagnostic marker for breast cancer as well as a marker and principal regulator of neural crest stem cells (NCSCs) playing an important role in the maintenance and migration of NCSCs." (PMID 27768723, 2016). "Protein overexpression of Slug, Sox9 and Sox10 were associated with poor overall survival and with triple-negative phenotype in breast cancer." (PMID 24404438, 2013). "Finally, we selected the transcription factor Sox10, as it has been implicated in the regulation of cell plasticity in mammary tumors." (PMID 36859337, 2023). "In conclusion, SOX10 is associated with breast cancer, stem cell and mitochondria function." (PMID 27768723, 2016). "Sox9, Sox10 and Slug were shown to be associated with poor overall survival in breast cancer." (PMID 24404438, 2013). "SOX10 is also expressed in breast carcinoma, which could pose another diagnostic challenge." (PMID 40507250, 2025). "In the context of breast carcinomas, GATA3 is predominantly expressed in hormone receptor-positive tumors (luminal A and luminal B) and HER2-positive carcinomas, while SOX10 serves as a hallmark stain for triple-negative (basal-like) carcinomas." (PMID 38902365, 2025). "It is also worth noting that the sensitivity of SOX10 is low in well-differentiated/low-grade breast carcinoma." (PMID 40025593, 2025). "The overall positive rate of SOX10 in breast cancer ranges from 6.5% to 40%, and is only about 60% in TNBC." (PMID 40822238, 2025). "It is notable that TRPS1 positivity was 100% in all special type breast cancers in this cohort, including metaplastic carcinoma, whereas the positivity rate of metaplastic carcinoma was low with SOX10 and GATA3." (PMID 40025593, 2025). "Studies show that its sensitivity is lower than TRPS1, but it can be used alongside SOX10 to help identify the basal-like subtype of breast cancer." (PMID 40822238, 2025). "SOX10 is a more recent addition to the immunohistochemical panel used in breast cancer, and it is particularly useful in the context of triple-negative breast carcinoma (TNBC)." (PMID 39518009, 2024). "While hormone receptors, mammaglobin, GATA3, and, in some cases, SOX10 remain the primary markers for most subtypes of breast carcinoma, TRPS1 has proven particularly useful in cases where these markers are either absent or equivocal." (PMID 39518009, 2024). "While TRPS1 is expressed in a wider range of breast cancer subtypes, the use of SOX10 is generally limited to specific TNBC cases, often as part of a broader panel including GATA3 and CK5/6." (PMID 39518009, 2024). "In cases where homozygous deletions and point mutations eliminate SOX10 staining presence, GATA3, a common marker in breast carcinoma, has been used in conjunction with SOX10 to address this limitation." (PMID 38132479, 2023). "SOX10 protein expression has also been observed in breast carcinomas, particularly in approximately 66–74% of triple-negative breast carcinomas." (PMID 38132479, 2023). "This is in agreement with previous studies demonstrating the role of SOX10 in regulating cell state plasticity in mammary tumors." (PMID 36859337, 2023). "Several studies have been conducted at the international level; however, no data are available in our population regarding the expression of SOX10 in breast carcinoma." (PMID 36120242, 2022).
breast carcinoma (continued). "SOX10 (SRY-related HMG-box 10) is a new marker advised for breast cancer, which according to a few studies has shown promising results in diagnosis." (PMID 36120242, 2022). "The possibility to target one or more of the genes that SOX10 controls as the basis for developing personalized therapy for metastatic breast cancer exists." (PMID 36120242, 2022). "We then mapped SOX10’s regulatory neighbourhood within the breast cancer transcriptome using weighted gene co-expression network analysis (WGCNA)." (PMID 35501337, 2022). "Our study has shown that it can be used to diagnose primary breast cancer at the metastatic site and can be used for SOX10-targeted treatment for TNBC." (PMID 36120242, 2022). "The expression of TRIM2 in basal-like breast carcinoma (BBC) is related to that of SOX10, and the expression of TRIM2 in breast cancer is clearly abnormal." (PMID 36051486, 2022). "In terms of genomic drivers of SOX10 expression in breast cancer, copy-number (CN) amplification or gain at the SOX10 locus was evident in ~20% of TNBCs and was associated with higher mRNA levels in both METABRIC and TCGA datasets (Fisher’s Exact p ≤ 0.001)." (PMID 35501337, 2022). "We explored the significance of SOX10 in breast cancer development and progression by immunophenotyping histologically normal breast tissue, and large breast tumour sample cohorts." (PMID 35501337, 2022). "Together, these studies suggest that the loss of SLK results in the activation of Sox9 that can directly induce Sox10 expression in murine tumors as well as human breast cancers." (PMID 33985544, 2021). "We and others have reported that triple-negative and basal/stem-like breast cancers can be defined by a high level of SOX10 expression." (PMID 33985544, 2021). "Recently, Sox10 has been shown to be expressed in mammary progenitor cells in vivo and be critical to maintain stemness in breast cancer." (PMID 33985544, 2021). "As we have shown that AKT activity is required for maintenance of Sox10 expression in SLK knockout mammary tumor cells, we first assessed the levels and nuclear localization of known transcription factors that are AKT-responsive." (PMID 33985544, 2021). "Supporting our findings in murine mammary tumors, we have also observed a correlation between pSox9 S181 levels and Sox10 expression in a proportion of HER2+ human tumor samples." (PMID 33985544, 2021). "As a transcription factor, SOX10 is mainly expressed in triple-negative and metaplasia breast cancer." (PMID 33344444, 2020). "This suggests that SOX9 and SOX10 are likely to act cooperatively to regulate cell fate plasticity in mammary stem/progenitor cells and breast cancer progression." (PMID 32521267, 2020). "SOX10 overexpression also induces reprogramming of cells in multiple mammary cancer models to an invasive, mesenchymal-like state that closely resembles a neural crest-like state." (PMID 32521267, 2020). "In our study, we showed that EYA2 was associated with CSCs markers YBX1, KLF5, and SOX10 in breast tumor tissues, and EYA2 overexpression up-regulated YBX1 in breast cancer cell lines." (PMID 30761270, 2019). "SOX10 is expressed in mouse and human breast cancers where tumor cells highly expressing SOX10 exhibit characteristics of MaSCs, EMT, and neural crest cells." (PMID 31013830, 2019). "To corroborate the findings drawn from our analysis, we performed immunohistochemical staining of a human breast cancer TMA for both SOX10 and AR." (PMID 30279965, 2018). "SOX10 expression is found in normal breast tissue and up to 40% of breast carcinoma, with enrichment in the unclassified triple-negative and metaplastic carcinomas." (PMID 29315345, 2018). "Understanding the mechanisms of SOX10 induction in breast cancers and the signaling that regulated SOX10 activity is a subject of ongoing research and will shed light on potentially new therapeutic targets for TNBC cancers." (PMID 30279965, 2018).
breast carcinoma (continued). "In our study we analyzed the prognostic role and stability of transcription factors as Sox9, Sox10 and Slug in a cohort of preoperative chemotherapeutically treated breast cancers." (PMID 24404438, 2013). "We analyzed immunohistochemical expression of Slug, Sox9 and Sox10 in tissue microarrays of 96 breast cancers prior to and after neoadjuvant chemotherapy." (PMID 24404438, 2013). "In this study we tested the stability of Slug, Sox9 and Sox10 expression during chemotherapy and addressed their prognostic role of in neoadjuvant treated primary breast-cancer and their correlation to pathological-response and overall survival." (PMID 24404438, 2013). "The aim of this study was to discover the prognostic role of Slug, Sox9 and Sox10 in neoadjuvantly treated breast cancer and the correlation to pathological response and overall survival." (PMID 24404438, 2013). "In contrast, GATA3, ER, PR, HER2, and SOX10 are important markers for identifying breast cancer." (PMID 41018104, 2025). "SOX10 was recently reported to have high expression in the triple negative breast cancer, which could be helpful for diagnosing the origin of breast cancer." (PMID 38539064, 2024). "Among carcinoma, SOX10 expression has been most frequently observed in salivary gland carcinoma and breast carcinoma, along with rare expression in head and neck squamous cell carcinoma, clear cell carcinoma, lung adenocarcinoma (LA), urothelial carcinoma, and colorectal carcinoma." (PMID 38813332, 2024). "Interestingly, several recent studies have shown that SOX10 is preferentially expressed in triple-negative and metaplastic breast carcinomas and has emerged as a useful immunohistochemical marker to utilize in breast pathology practice." (PMID 36859337, 2023). "Therefore, this study aimed to assess SOX10 expression in TNBC to classify breast cancer, specifically metastatic TNBC, for pathological diagnosis in routine surgical specimens." (PMID 36120242, 2022). "SOX10 expression may lead to confusion in diagnosis but many studies have proven that breast carcinomas, particularly basal-like, triple-negative phenotypes, are also labeled by SOX10." (PMID 36120242, 2022). "Consistent with our TCGA analysis and murine data, we observed that 43% of TNBC cores were Sox10hi and that all Sox10hi nuclei in those cores also showed a pSox9 S181hi signal, suggesting that the activation of Sox9 and Sox10 induction is also observed in human breast cancer samples." (PMID 33985544, 2021). "Recently, Sox10 was found to be specifically expressed in mammary progenitor cells, including fetal and adult mammary cells in vivo and be critical to maintain the stem cell state and reprogramming in breast cancer." (PMID 33985544, 2021). "Interestingly, analysis of murine and human mammary tumors reveals a direct correlation between the levels of active phospho-Sox9 S181 and Sox10 expression." (PMID 33985544, 2021). "If Sox10 and Sox9 have discrete functions within basal or luminal progenitors in the normal gland, they may also have discrete functions in breast cancer subtypes that differ in their contributions of basal and luminal cells." (PMID 33082503, 2020). "Interestingly, a recent paper identified parallels between mammary cell tumorigenesis and neural crest lineage, by showing that SOX10 expression correlates with invasiveness and can elicit neural crest-like features in mammary tumours." (PMID 32714600, 2020). "In addition, JAG1 and SOX10 can induce mesenchymal features, and have been found to promote the migratory and invasive abilities of breast cancer cells." (PMID 30602372, 2019). "SOX2 and SOX10 are often present in breast cancer, although their role is poorly understood yet." (PMID 29739401, 2018). "Further prognostic role of Sox10 in breast cancer, needs to be addressed in future studies." (PMID 24404438, 2013).